RN7SKP181 (RN7SK pseudogene 181)
Gene: Miscellaneous RNA gene on chromosome 15 (96,842,069 to 96,842,384, forward strand). Ensembl gene ENSG00000223120.
Homologues: Orthologues: chimpanzee 7SK (98% identical). Paralogues in human: RN7SKP180 (72% identical), RN7SKP71 (72% identical), RN7SKP204 (72% identical), RN7SKP250 (71% identical), RN7SKP79 (71% identical), RN7SKP203 (71% identical), RN7SKP255 (71% identical), 7SK (70% identical), RN7SKP124 (70% identical), RN7SKP185 (70% identical), RN7SKP25 (70% identical), RN7SKP75 (69% identical), and 284 more.